CXXC5 (CXXC finger protein 5)
Diseases named in the same sentence as CXXC5 in open-access papers (continued):
Sharing a sentence is not in itself a finding about the gene and the disease.
myelodysplastic syndrome (3 papers, 2013 to 2025). A clonal hematopoietic disorder characterized by dysplasia and ineffective hematopoiesis in one or more of the hematopoietic cell lines. "Lenalidomide was also investigated because this drug is used in the treatment of patients with myelodysplastic syndrome (MDS) and the del(5q) abnormality that leads to loss of one CXXC5 gene and low CXXC5 expression." (PMID 25605239, 2015).
pulmonary fibrosis (3 papers, 2020 to 2025). Chronic progressive interstitial lung disorder characterized by the replacement of the lung tissue by connective tissue, leading to progressive dyspnea, respiratory failure, or right heart failure. "We successfully constructed the CXXC5 overexpression group through an adenoviral vector and further studied the role of CXXC5 in the progress of pulmonary fibrosis." (PMID 32337277, 2020). "At the same time, overexpression of CXXC5 reduced the content of hydroxyproline in lung tissue and decreased the score of pulmonary fibrosis, indicating that CXXC5 can inhibit the progression of pulmonary fibrosis and has an antifibrotic effect." (PMID 32337277, 2020). "By RT-PCR and Western blot, we found that CXXC5 expression was low in the bleomycin-induced pulmonary fibrosis model and in vitro pulmonary fibrosis model, showing that CXXC5 was involved in pulmonary fibrosis." (PMID 32337277, 2020). "There are few studies on pulmonary fibrosis in CXXC5 locally and abroad, and the role and mechanism of CXXC5 in pulmonary fibrosis are unclear." (PMID 32337277, 2020). "Additionally, CXXC5 exerts an antifibrotic effect by inhibiting CD40/CD40L during the development of bleomycin-induced pulmonary fibrosis in mice." (PMID 39806388, 2025). "It was confirmed that overexpression of CXXC5 inhibited BLM-induced pulmonary fibrosis." (PMID 32337277, 2020). "Therefore, we conclude that overexpression of CXXC5 inhibits the development of pulmonary fibrosis by downregulating the CD40/CD40L pathway." (PMID 32337277, 2020). "Thus, CXXC5 overexpression inhibited the activation of the CD40/CD40L signaling pathway in a mouse model of pulmonary fibrosis." (PMID 32337277, 2020). "Therefore, we hypothesize that CXXC5 may participate in the development of pulmonary interstitial fibrosis through the CD40/CD40L pathway and explore the role of the CXXC5/CD40/CD40L pathway in an in vitro and in vivo fibrosis model." (PMID 32337277, 2020). "The BLM+Ad-GFP group suffered from more severe alveolar structural damage and had more collagen fibers and higher pulmonary fibrosis score and hydroxyproline content than the BLM+Ad-CXXC5 group, and the difference was statistically significant (P < 0.05)." (PMID 32337277, 2020). "By comparing HE staining, Masson staining, hydroxyproline content, and pulmonary fibrosis score in lung tissue, we identified that the BLM+Ad-CXXC5 group had significantly reduced alveolar damage collagen deposition compared with the BLM group." (PMID 32337277, 2020). "Based on the results of cell and animal experiments, we found a significant increase in CD40 and CD40L in the model of in vitro and in vivo pulmonary fibrosis and a significant decrease in CD40 and CD40L when CXXC5 was overexpressed." (PMID 32337277, 2020). "Overexpression of CXXC5 inhibited the progression of bleomycin-induced pulmonary fibrosis in mice by inhibiting the CD40/CD40L signaling pathway, which is possibly a new target for the treatment of pulmonary fibrosis." (PMID 32337277, 2020). "CXXC5 inhibits pulmonary fibrosis and transformation to myofibroblasts by negative feedback regulation of the CD40/CD40L pathway." (PMID 32337277, 2020). "We conducted further studies to explore whether CXXC5 exerted antifibrotic effects through the negative regulation of CD40/CD40L and found that CD40 and CD40L were upregulated in the pulmonary fibrosis model both in vitro and in vivo, but CD40 and CD40L were downregulated after CXXC5 overexpression." (PMID 32337277, 2020). "Thus, CXXC5 overexpression can inhibit the expression of α-SMA and Colla I in pulmonary fibrosis." (PMID 32337277, 2020).
androgenetic alopecia (2 papers, 2023 to 2025). "Taken together, we identified that DHT and PGD2, the major inducers of androgenetic alopecia, cause hair loss by Wnt/β-catenin signaling suppression via CXXC5 overexpression." (PMID 36831222, 2023). "Overall, considering the role of CXXC5 as an important mediator of DHT action and phenotypical outcomes, the inhibition of CXXC5 function is a potential treatment for androgenetic alopecia." (PMID 36831222, 2023). "In addition, dihydrotestosterone (DHT) has been discovered to upregulate CXXC5 expression via the DHT-PGD2-Smad1/5/9 axis in human immortal keratinocyte line (HaCaT), thereby inhibiting Wnt signaling via CXXC5-Dvl interaction and mediating androgenetic alopecia." (PMID 39806388, 2025).
astroblastoma (2 papers, 2021 to 2024). "In the fifth CNS WHO classification, MN1 is part of the diagnosis of a “circumscribed astrocytoma”, Astroblastoma MN1-altered, characterized by fusions of MN1 with BEND2 or CXXC5 genes." (PMID 39409964, 2024).
colon carcinoma (2 papers, 2021 to 2025). "In human colon cancer cells, CXXC5 expression is upregulated by β-catenin, and the β-catenin/T-cell factor 4 (TCF4) complex has been discovered to coordinate with a chromatin loop integrated 5' and 3' Wnt responsive DNA enhancers (WREs)." (PMID 39806388, 2025).
colorectal cancer (2 papers, 2023). A primary or metastatic malignant neoplasm that affects the colon or rectum. "The role of CXXC5 in colorectal cancer will require further study." (PMID 38054820, 2023).
diabetes (2 papers, 2022 to 2023). "CXXC5 was highly expressed in subcutaneous and visceral adipose tissues of the obese‐diabetes patients especially at the F4/80+ crown‐like structures (CLSs) of adipose tissues, compared to that in lean non‐diabetic subjects." (PMID 35384342, 2022). "Our current reports that CXXC5, a negative regulator of the Wnt/β‐catenin pathway functioning via Dvl binding, is highly expressed in visceral adipose tissues of obese‐diabetes patients." (PMID 35384342, 2022). "Expression level of CXXC5 was characterised in clinical samples and diabetes‐induced mice model." (PMID 35384342, 2022). "In addition, small molecular mimetics of PTD-DBM peptide that interferes the function of CXXC5, such as KY19382 and KY19334, induce wound healing, hair growth, and longitudinal bone growth, and improve metabolic abnormalities, including diabetes, by activating Wnt/β-catenin signaling." (PMID 37524876, 2023).
myelocytic leukemia (2 papers, 2016 to 2020). "Identified as a novel, all-trans retinoic acid (ATRA)-responsive gene, the CXXC5 protein was shown to be involved in ATRA-induced terminal differentiation of myelocytic leukemia cells, and in cytokine-driven physiological myelopoiesis." (PMID 27886276, 2016).
osteoporosis (2 papers, 2016 to 2019). A condition of reduced bone mass, with decreased cortical thickness and a decrease in the number and size of the trabeculae of cancellous bone (but normal chemical composition), resulting in increased fracture incidence. "We previously identified that CXXC5 is a negative feedback regulator of the Wnt/β‐catenin pathway via its interaction with Dishevelled (Dvl) and suggested the Dvl–CXXC5 interaction as a potential target for anabolic therapy of osteoporosis." (PMID 26941261, 2016). "In conclusion, we identified the indole‐containing small molecules as candidates of orally deliverable anti‐osteoporosis agents, activating the Wnt/β‐catenin signaling via inhibition of Dvl–CXXC5 interaction." (PMID 26941261, 2016). "In conclusion, small‐molecule inhibitors of the Dvl–CXXC5 interaction that block negative feedback regulation of Wnt/β‐catenin signaling are potential candidates for the development of bone anabolic anti‐osteoporosis drugs." (PMID 26941261, 2016).
thyroid cancer (2 papers, 2015 to 2025). "Conversely, CXXC5 is highly expressed in metastatic melanoma, thyroid carcinoma (THCA), BC, endometrial cancer (EC), PCa, and ovarian cancer (OC), suggesting a potential tumor-promoting function." (PMID 39806388, 2025). "Furthermore, disparities in CpG methylation within the CXXC5 promoter were identified in prostate, bladder, and thyroid cancers compared to normal tissues, indicating that methylation may play a role in regulating CXXC5 expression." (PMID 39806388, 2025).
acute promyelocytic leukemia (1 paper, 2025). An aggressive form of acute myeloid leukemia (AML), characterized by arrest of leukocyte differentiation at the promyelocyte stage, due to a specific chromosomal translocation t(15;17) in myeloid cells. "All-trans retinoic acid (ATRA) can directly induce the expression of CXXC5, which has been shown to play an important role in ATRA-induced terminal differentiation of acute promyelocytic leukemia (APL) cells." (PMID 39806388, 2025).
alopecia (1 paper, 2023). Hair loss usually from the scalp. "Similar to other alopecia factors, Cxxc5 increases in the late anagen phase to induce the catagen phase and the CXXC5 level is elevated in alopecia patients." (PMID 36831222, 2023). "We also found that DHT-induced alopecia was alleviated by treatment with KY19382, a small molecule mimetic of PTD-DBM which induces hair growth by simultaneous inhibition of the functions of CXXC5 and GSK-3β." (PMID 36831222, 2023).
Alzheimer disease (1 paper, 2025). A progressive, neurodegenerative disease characterized by loss of function and death of nerve cells in several areas of the brain leading to loss of cognitive function such as memory and language. "Inhibition of the CXXC5-Dvl interaction resulted in a notable improvement in the Alzheimer's disease status of the 5xFAD mice." (PMID 39806388, 2025). "Furthermore, CXXC5 is involved in the pathogenesis of Alzheimer's disease (AD)." (PMID 39806388, 2025).
chronic myeloid leukemia (1 paper, 2015). "In our present study we compared CXXC5 expression in chronic myeloid leukemia cells; we then used previously published global gene expression data." (PMID 25605239, 2015).
COVID-19 (1 paper, 2025). A disease caused by infection with severe acute respiratory syndrome coronavirus 2. "Using the gene expression omnibus (GEO) database Cantu et.al identified down-regulation of several skeletal muscle-related genes, including FOX01, Malat1, TIN and CXXC5 in patients with COVID-19." (PMID 39179952, 2025).
diffuse intrinsic pontine glioma (1 paper, 2025). A neuroglial tumor that arises from the middle portion of the brain stem. "Furthermore, Induction of CXXC5 expression by TGF-β1/BMP signaling has also been observed in Hep3B, HepG2, and diffuse intrinsic pontine glioma (DIPG) cell lines." (PMID 39806388, 2025).
esophageal squamous cell carcinoma (1 paper, 2025). Esophageal squamous cell carcinoma (ESCC) is a type of esophageal carcinoma (EC) that can affect any part of the esophagus, but is usually located in the upper or middle third. "In esophageal squamous cell carcinoma (ESCC), upregulated miR-32 can target the 3'-UTR of CXXC5 to inhibit CXXC5 expression and is associated with increased capacity of migration, invasion and adhesion in ESCC." (PMID 39806388, 2025).
gastric cancer (1 paper, 2025). A primary or metastatic malignant neoplasm involving the stomach. "CXXC5 is expressed at low levels in hematopoietic system tumors, gastric cancer (GC), and DIPG, indicating a potential tumor-suppressive role." (PMID 39806388, 2025).
Hepatic steatosis (1 paper, 2022). Steatosis is a term used to denote lipid accumulation within hepatocytes. "Thus, HFD‐induced adipocyte hypertrophy and hepatic steatosis were abrogated in Cxxc5−/− mice." (PMID 35384342, 2022). "Differently with Cxxc5+/+ mice, Cxxc5−/− mice did not exhibit significant hepatic steatosis induced by the HFD." (PMID 35384342, 2022).
Immunodeficiency (1 paper, 2023). Failure of the immune system to protect the body adequately from infection, due to the absence or insufficiency of some component process or substance. "Remarkably, heterozygous de novo variants of the CXXC5 gene are implicated in several childhood pathological processes, including immunodeficiency, sinusitis, and recurrent otitis media, as well as occasional pneumonia, suggesting a vital role for CXXC5 in development." (PMID 36539038, 2023).
myeloid malignancies (1 paper, 2025). "In myeloid malignancies, EZH2 regulates CXXC5 expression and influences disease development, and the mutation status of EZH2 affects CXXC5 expression." (PMID 39806388, 2025).
psoriasis (1 paper, 2025). An autoimmune condition characterized by red, well-delineated plaques with silvery scales that are usually on the extensor surfaces and scalp. "Its mention in the current context is therefore likely a new finding, making CXXC5 a potentially novel gene association for psoriasis." (PMID 41328434, 2025). "Additional Mendelian randomization analysis pinpointed seven marker genes linked to psoriasis: BIN2, CAPN12, CXXC5, KLRC1, KLRD1, PRF1, and SLFN5." (PMID 41328434, 2025). "CXXC5, KLRC1, along with five additional genes, are linked to a reduced risk of psoriasis." (PMID 41328434, 2025). "Overall, these results argue against a predominant psoriasis → expression direction and are instead consistent with expression → psoriasis; CXXC5 may reflect disease-driven transcriptional feedback and warrants further validation." (PMID 41328434, 2025). "Despite this immune relevance, CXXC5 has not been previously linked to psoriasis in genome-wide studies or expression profiling." (PMID 41328434, 2025). "By integrating single-cell RNA sequencing with MR analysis, we identified seven psoriasis-related genes (BIN2, CAPN12, CXXC5, KLRC1, KLRD1, PRF1, and SLFN5) that are highly expressed in CD4+ T cells." (PMID 41328434, 2025). "The seven genes span established–emerging–novel tiers: PRF1 and KLRC1/KLRD1 are established in psoriasis immunity; SLFN5 is a recently reported systemic inflammatory marker; BIN2/CXXC5/CAPN12 lack prior links, suggesting novelty." (PMID 41328434, 2025). "Notably, CXXC5 is highly expressed in plasmacytoid dendritic cells (pDCs) and is crucial for robust interferon responses to TLR7/9 stimulation (pDCs are one of the initiating immune cell types in psoriasis, as self-DNA/RNA induced pDC activation has been implicated in psoriatic plaque development)." (PMID 41328434, 2025). "This antagonistic regulatory pattern suggests that CXXC5 and SLFN5 may play complementary roles in balancing CD4+ T cell activation and homeostasis, highlighting their potential functional relevance in psoriasis and other immune-related diseases." (PMID 41328434, 2025). "There are no known psoriasis GWAS hits or published functional studies for CXXC5 in this disease." (PMID 41328434, 2025).
rhabdoid tumor (1 paper, 2024). An aggressive malignant embryonal neoplasm usually occurring during childhood. "An AT/RT-specific DM-DE gene CXXC5 also harbors binding sites of several neural TFs, SMARCA4 binding sites in rhabdoid tumor cells, and both PSC-like and AT/RT-unique DMRs." (PMID 38499326, 2024).
steatosis (1 paper, 2022). Increased lipid within the cytoplasm of cells. "The NAS implied that other NASH phenotypes, including steatosis, ballooning, and inflammation, were lowered in Cxxc5−/− mice." (PMID 36114279, 2022). "A reduction in hepatosteatosis was observed in parallel with lower steatosis and ballooning scores in Cxxc5−/− mice." (PMID 36114279, 2022). "Multiple pathological phenotypes of NASH, including inflammation, steatosis, oxidative stress responses, and fibrosis, were not significantly observed in Cxxc5−/− mice." (PMID 36114279, 2022).
viral infection (1 paper, 2021). "Epigenetic regulator CXXC finger protein 5 (CXXC5) recruits TET2 to maintain hypomethylation of CpG islands (CGI) in the genome of plasmacytoid dendritic cells (pDCs), a rare subset of DCs that highly produce IFN-α in response to viral infection." (PMID 33085059, 2021).
tumor (18 papers, 2012 to 2025). "Furthermore, the expression of CXXC5 was associated with immune cell infiltration, suggesting a potential involvement of CXXC5 in anti-tumor immunity in CML." (PMID 39806388, 2025). "Notably, depletion of CUL4B or MTA1 in CXXC5-overexpressing tumors led to a diminished effect of CXXC5 overexpression; consistently, the decrease in tumor growth associated with CXXC5 knockdown could be rescued by the simultaneous silencing of TSC1." (PMID 36539038, 2023). "The expression of CXXC5 is significantly upregulated in patients with advanced BC, and its high expression correlates with higher tumor grade and poorer prognosis in BC patients." (PMID 39806388, 2025). "In terms of tumor therapy, it is currently predictable that CXXC5 has essential value in tumor diagnosis." (PMID 39806388, 2025). "In the context of BC diagnosis, CXXC5 expression is significantly elevated in patients with advanced stages of BC, and its high expression correlates with higher tumor grade and poorer prognosis in patients." (PMID 39806388, 2025). "Mechanistically, KANK1 plays a tumor suppressor role in various tumors and positively regulates the expression of CXXC5." (PMID 39806388, 2025). "CXXC5 is a potential tumor suppressor in GC, and CXXC5 expression is downregulated in GC tissues and cells." (PMID 39806388, 2025). "NUDT21 inhibited HCC proliferation, metastasis and tumorigenesis, at least in part, by suppressing proteasome subunit beta type-2 (PSMB2) and CXXC-type zinc finger protein 5 (CXXC5), acting as a tumor suppressor in hepatocellular carcinogenesis." (PMID 32346127, 2020). "CXXC5 has been found to act as an oncogene in some cancers and as a tumor suppressor in others." (PMID 39806388, 2025). "The impact of CXXC5 in cancer results from its dual mechanism of action (oncogene and tumor suppressor), which may reduce its inhibitory potential when attempting to inhibit its cancer-promoting activity." (PMID 39806388, 2025). "Furthermore, CXXC5 is indicative of different tumor types and is highly expressed in ER+ BC patients compared to basal-like and triple-negative BC." (PMID 39806388, 2025). "The results showed that compared with the vector, CXXC5 overexpression was associated with a significant increase in the growth of primary MCF-7 tumors, whereas CXXC5 knockdown was accompanied by a decrease in the tumor growth." (PMID 36539038, 2023). "Mechanistically the authors proposed that by the epigenetic upregulation of the tumour suppressor CXXC5, the BMP4-response could be mediated." (PMID 36497175, 2022). "Therefore, CXXC5 is considered to be a tumor inhibitor, involved in apoptosis, but the specific mechanism is unclear." (PMID 32337277, 2020). "PFKFB2 and CXXC5 were hypomethylated in both tumor groups compared to NT and BTL." (PMID 30884810, 2019). "Those genes showing high expression in CXXC5HIGH primary human AML cells and being significantly altered (i.e. increased) after CXXC5 knockdown included one potential tumor suppressor (TSC22), the cytokine Angiopoietin 1, a selenium transport protein and the hematopoietic growth factor receptor KIT." (PMID 25605239, 2015). "In addition, we also showed that CXXC5 is involved in tumor-immune regulation." (PMID 36539038, 2023). "However, downregulated expression of CXXC5 is associated with low-risk abnormalities and higher overall survival in patients with newly diagnosed AML receiving intensive chemotherapy, indicating that CXXC5 may act as a tumor suppressor involved in tumor development." (PMID 39806388, 2025).